CD4 (CD4 molecule)
Diseases named in the same sentence as CD4 in open-access papers (continued):
Sharing a sentence is not in itself a finding about the gene and the disease.
tumor (continued). "Despite the low baseline abundance of CD4+ and CD8α+ T cells in tumors (<1% of CD45+ cells), treatment with anti‐mPD‐1 mAb significantly delayed both tumor progression and recurrence." (PMID 41208884, 2025). "Our analysis revealed that CD4 + and CD8 + T cells in closer proximity to the tumor core during treatment exhibited greater activation, potentially accompanied by negative feedback upregulation of LAG3 expression." (PMID 40411616, 2025). "Second, mannose-modified stearic acid-grafted chitosan micelles (MChSA) overcome antigen uptake limitations by DCs, enabling targeted delivery to tumor-draining lymph nodes (TDLN) and inducing robust CD4+/CD8+ T-cell responses with tumor growth inhibition." (PMID 41149588, 2025). "The remodeling of tumor blood vessels and anti-angiogenic effects of anti-CTLA-4 antibodies require the presence of CD4+ T cells and the activity of IFNγ, a potent anti-angiogenic cytokine." (PMID 40460830, 2025). "For example, a gradual shift of many CD4 + and CD8 + T cells towards dysfunctional states and a strong corresponding link to tumor reactivity were found." (PMID 40954493, 2025). "This analysis revealed that decreased numbers of CD4+ and CD3+ T-cells correlated with a reduction in tumour volume, again emphasising the role of the immune response in this setting." (PMID 40468999, 2025). "Most importantly, DAC and IL-33 synergistically enhanced the expression of PD-1 within the TME and the percentages of PD-1 expressing tumor-infiltrating CD8 and CD4 T cells, resulting in improved in vivo response to PD-1 blockade." (PMID 40317004, 2025). "This combinatorial strategy enhanced cytotoxicity against 4T1 breast cancer cells, increased CD4+ and CD8+ T-cell infiltration, induced immune memory, inhibited lung metastasis, and achieved sustained antitumor efficacy with the tumor volume reduced up to 70%." (PMID 41471822, 2025). "Enhancing the proliferative and anti-tumor capabilities of effector T cells can be accomplished by targeting the elevated expression of LAG3 on CD8+ and CD4+ T cells in the bone marrow and blood of patients with multiple myeloma." (PMID 41019045, 2025). "We examined the correlations between expression of CD4, CD8, and CD34 and tumor margin infiltration observed on a DWI sequence." (PMID 40362599, 2025). "There was a significant correlation between high LAG3 expression and active CD4 + and CD8 + T cells in tumor cells." (PMID 40411616, 2025). "Tregs, defined as CD4+ T lymphocytes expressing CD25 and the transcription factor Foxp3, engage dynamically with tumor cells and extracellular matrix components." (PMID 41320679, 2025). "Effective antitumor immunity depends on the coordinated activation of tumor antigen (Ag)-specific CD8+ cytotoxic T lymphocytes (CTLs) and CD4+ helper T cells, which recognize antigens presented by HLA class I and II proteins, respectively." (PMID 40801653, 2025). "These antibodies also function as antigen-presenting cells, presenting tumor antigens to CD4+ T cells through MHC class II molecules, indirectly activating CD8+ T cells and enhancing the overall immune response against the tumor." (PMID 40255905, 2025). "They noted worse survival in patients with high PD-L1 and LAG-3 expression along with low CD3, CD4, and ICOS expression, especially in the tumor center." (PMID 39751894, 2025). "In addition, we could detect more CD4+ T cells in direct contact or close to PC+ tumor cells." (PMID 39789356, 2025). "CD8+ T cells can recognize specific exogenous antigens that CD4+ cells cannot, such as those from MHC I. CD8+ T cells work directly to target tumor cells by recognizing MHC I receptors on the tumor cell surface through the activation of the TCR complex." (PMID 40565098, 2025). "The combination of 6lc and CAR.CD19-T cells markedly improved tumor control and increased infiltration of both CAR T and CD4+ T cells." (PMID 41148213, 2025).
tumor (continued). "Indeed, lactate can contribute to tumour evasion by altering the metabolism and function of cytotoxic T lymphocytes (CTLs), concurring to macrophage polarisation towards a pro‐tumoural M2‐like phenotype and favouring an enrichment in CD4 immunosuppressive Tregs." (PMID 39888245, 2025). "Consistently, microscopic images of the immunofluorescence staining demonstrated that the population of CD4+, CD8+ tumor-infiltrating lymphocytes and IFN-β expression were markedly enhanced via US-initiated SPDT synergized with STING agonists." (PMID 40739587, 2025). "Although transplant immunology is intriguing, the role of protocolised liver biopsies and assessment of the CD4/CD8 ratios, tumour infiltrating lymphocytes and PD‐L1 expression post‐LT for prediction of graft rejection is yet to be evaluated." (PMID 40808313, 2025). "These collective observations strongly suggest that HO-1 inhibition increases CD4+ and CD8+ T cells infiltration in the tumor tissues." (PMID 40037158, 2025). "In C57BL/6 mice, the percentage of CD4+ T and CD8+ T cells in the tumor microenvironment was significantly elevated in the PRMT5 knockdown group compared to the control group." (PMID 41463372, 2025). "To examine this, primary CD4+ T cells were transduced with TCR1, a high-affinity TCR which we have previously shown can mediate tumor rejection in the context of ACT, or with either TCR16 or TCR18, each of which were isolated from a single FoxP3+ cell." (PMID 40196575, 2025). "CD4+ and CD8+ CAR T cells were magnetically sorted from pooled blood samples of the tumor-bearing mice (day 28)." (PMID 40107240, 2025). "OX40 signaling further enhanced the function and migration of activated CD4+ and CD8+ T cells in the presence of tumor antigens, leading to low-level antigen cross-recognition and inflammation in normal tissues such as intestine, skin and liver." (PMID 41561762, 2025). "Analyses of TCGA data and our data from in vivo experiments have demonstrated that apCAFs in the HNSCC can influence the ratio of CD4+/CD8+ T cells, ultimately promoting tumor growth." (PMID 39891284, 2025). "Overall, response to multiple checkpoint and myeloid blockades is driven by both CD4 and CD8 T cells, including T cells expressing TCF, ICOS, PD-1 and KI67, as well as neutrophils and MHC+ macrophages, and MHC expression by tumor cells." (PMID 40027748, 2025). "HA suppresses naïve CD4+ T cell differentiation into Tregs, reduces the immunosuppressive activity of Tregs against CD8+ T cells, and decreases tumor infiltration of Tregs." (PMID 40847888, 2025). "Together, the findings suggest that myeloid Tgfbr2 deletion enhances CD103+ DCs function and activates CD4+ and CD8+ T cells leading to an IFN-γ rich tumor microenvironment." (PMID 40568095, 2025). "While lower doses of anti-VEGF therapy in vivo results in vessel normalisation, improved tumour perfusion and the promotion infiltration of CD8+ and CD4+ T cells restoring an immunosupportive environment." (PMID 40328959, 2025). "tumor destruction and the presence of many SRC-3-KO-Tregs, CD8 cells, CD4 cells, natural killer cells, cytokines, and very high Inf-γ." (PMID 40090583, 2025). "Cell-cell communication analysis demonstrated that CD4+ T cells, CD8+ T cells and tumor epithelial cells were central hubs in the interaction network, exhibiting the highest number of intercellular connections." (PMID 40909272, 2025). "Within the tumor primary lesion, TIM-1+CD4+ T cells, TIM-1+CD8+ T cells, and TIM-1+B cells were predominantly found in the stromal area." (PMID 40519901, 2025). "The antitumor efficacy of the DC vaccine is believed to be impeded by the immunosuppressive tumor microenvironment, which suppresses antigen cross-presentation and the activity of antigen-specific CD8+ and CD4+ T-lymphocytes within the tumor stroma." (PMID 40918451, 2025).
tumor (continued). "The co-inhibitory receptors LAG-3, PD-1, and TIM-3 were expressed by significantly higher proportions of CD4+ and CD8+ T lymphocytes in tumor tissue and ascites compared to peripheral blood." (PMID 40649775, 2025). "As seen with ICB-treated heterozygous Map3k7f/wt KPPC tumors, the combination of Takinib and ICB resulted in higher infiltration of total and proliferating CD4+ and CD8+ T cells, as well as closer proximity between proliferating CD8+ T and tumor cells." (PMID 41280086, 2025). "In tumor-draining lymph nodes, activated APCs, particularly dendritic cells, present tumor antigens via MHC class I molecules to CD8+ T cells and via MHC class II molecules to CD4+ T cells." (PMID 40896696, 2025). "Conversely, the low-risk group displayed increased proportions of monocytes, activated CD4 memory T cells, resting dendritic cells, M1 macrophages, and resting mast cells, indicating that the TME changed to a more tumor-suppressive phenotype." (PMID 40028163, 2025). "In vivo studies showed that mice treated with FRα-specific CAR-T cells had higher levels of human CD4+ and CD8+ T-cells in the blood, reduced tumor growth, and stable FRα expression." (PMID 40281554, 2025). "A greater degree of CD4+ and CD8+ T cell colocalization was observed in the CTT group than in the tumor-bearing group." (PMID 40277945, 2025). "In the tumor microenvironment (TME), SUSD3 is predominantly expressed in monocytes/macrophages and CD4+ T cells." (PMID 40191190, 2025). "Results showed that the expression of GINS1 was correlated with tumor purity (r = 0.179), B cell (r = 0.479), CD8+ T cell (r = 0.335), CD4+ T cell (r = 0.344), macrophage (r = 0.46), neutrophil (r = 0.373), dendritic cell (r = 0.480) (all p < 0.05)." (PMID 40123906, 2025). "Similarly, the decreased CD4/CD8 ratio in all patients from the exercise group after neoadjuvant chemotherapy might suggest an increased proportion of cytotoxic CD8+ T cells relative to helper or regulatory CD4+ T cells in the tumour." (PMID 40510180, 2025). "Flow cytometry analysis of tumor-infiltrating immune cells showed that Pin1 inhibitor monotherapy increased infiltration of CD3+ lymphocytes, CD8+ T cells, and CD4+ T cells." (PMID 41246306, 2025). "Patient-specific variables (e.g. age, prior treatments) can alter the CD4+/CD8+ composition, with a balanced ratio shown to improve anti-tumor responses." (PMID 41346587, 2025). "Adding dual-PI3Kδ/γ inhibitor Duvelisib during CAR T cell manufacture yields cells with an enhanced number of memory subsets, normalized CD4/CD8 ratios, increased mitochondrial mass, and epigenetic modifications correlating with enhanced anti-tumor efficacy." (PMID 41346587, 2025). "Flow cytometric analysis confirmed the increase of CD4+, CD8+ and neutrophils (CD11bhighLy‐6Ghigh) in the KAR tumours while the percentage of macrophages was similar." (PMID 40621620, 2025). "After anlotinib treatment, interactions among M01–M07 myeloid cells, CD4+ and CD8+ T cells, and C1 and C2 tumor cells increased notably." (PMID 40260248, 2025). "CXCR5+ PD-1+ Tfh-like cells that made up a minor fraction of total CD4+ T cells were a significant component of the CLTCH129>Q-specific response, and these also subsequently deceased during progressive tumor growth." (PMID 40196575, 2025). "Specifically, a high infiltration of CD8+, CD4+, and CD3+ T lymphocytes localized in the margin and the core of the tumor has been correlated with a prolonged time in therapeutic range, increased OS, and DFS." (PMID 40218263, 2025). "In the tumor parenchyma, the infiltrating immune cells were primarily CD68+ macrophages; while in the stroma, CD4+ T cells were dominant." (PMID 40710213, 2025). "For these purposes, CD4 and CD8 T lymphocytes were isolated and sorted from HCC tumor tissue, HCC-free tissue areas, and healthy liver tissue, as well as from the peripheral blood mononuclear cells (PBMCs) of HCC patients and healthy donors." (PMID 40352930, 2025).
tumor (continued). "Beyond its role in tumor biology, CCR5 is also essential for the generation of effective T cell–mediated antitumor responses; its expression in both CD4+ and CD8+ T cells is required to achieve maximal immune function within the tumor microenvironment (TME)." (PMID 41149503, 2025). "Collectively, these results indicate that 130H2 treatment enhances the infiltration of DCs, NK cells, CD4 + T cells, CD8 + T, and M1 macrophages into the tumor microenvironment, effectively reversing its immunosuppressive phenotype." (PMID 39743547, 2025). "We identified 11 cell subpopulations: CD4 T cells, Tregs, B cells, CD8 T cells, tumor cells, plasma cells, monocytes, fibroblasts, endothelial cells, mast cells, and smooth muscle cells." (PMID 41174721, 2025). "In certain contexts, CD4+ T cells can also acquire cytotoxic potential via expression of perforin and granzyme B, directly killing MHC class II+ tumor cells." (PMID 40660400, 2025). "In turn, TAMs secrete high levels of IL10 and transforming-growth factor (TGF)-ß that decrease the activation of CD4+ and CD8+ T cells during tumor progression and bone metastasis formation." (PMID 40902549, 2025). "For instance, the PI3KCA inhibitor AMG319 can lead to the activation of CD4+ and CD8+ T-cell responses and a weakening of the function of tumor-infiltrating Tregs." (PMID 40083325, 2025). "Sequential biopsies demonstrated increased CD8+ T and CD4+FOXP3− T-cell infiltration and granzyme B (GZMB) overexpression, indicating tumour immunity activation by visugromab." (PMID 41294666, 2025). "During the tumor proliferation phase, within the TME, appropriate ROS concentration is crucial for the activation of T cells (CD4+ T cells and CTL), which are key effectors of anti-tumor immunity." (PMID 40424719, 2025). "Another CD4+ T cell subset, Th1, supports the immune response mainly by promoting CD8+ T cell activation and stimulating anti-tumour immune responses." (PMID 40495147, 2025). "The presence of effector memory T cells (including CD4+ Tem and CD8+ Tem) is essential for maintaining long-term anti-tumor immune responses." (PMID 41347075, 2025). "Secondary transplanted T4M28zT2 T cells inhibited tumor growth better than CD3+ M28zT2, CD4+ T28zT2, or CD3+ 1928zT2 T cells alone." (PMID 40107245, 2025). "Coculture of TILs with autologous tumor digest resulted in significantly increased CD137 expression in all T-cell subsets when compared to medium control (CD8+ T cells: P = 0.02; CD4+ T cells: P = 0.05; γδ T cells: P = 0.02)." (PMID 40897471, 2025). "Tumor-secreted soluble factors, such as transforming growth factor-beta (TGF-β) and PD-L1, can induce FOXP3 expression in conventional CD4+ T cells, resulting in the generation of Tregs with immunosuppressive capabilities." (PMID 40867165, 2025). "We identified clusters of TCF1+ T cells (including both CD4+ and CD8+ T cells) and of TCF1− CD8+ T cells and projected them on the tumour space." (PMID 40745918, 2025). "Consistently with our in vitro findings on the ability of CM272 to enhance PDAC cells immunogenicity, we observed a marked infiltration of CD4 + and CD8 T + cells in the tumour tissues of CM272-treated animals." (PMID 39810240, 2025). "TLR9 agonists have been demonstrated to augment the number of DCs, CD4+, and CD8+ T Cells following radiotherapy, thereby enhancing the local and systemic anti-tumor effects of RT." (PMID 40356601, 2025). "To assess the specific T cell subpopulations involved in the mechanism of HVEM-Fc treatment, we further depleted CD4+ T cells, CD8+ T cells, or CD25+ Tregs in tumor-bearing mice receiving HVEM-Fc treatment." (PMID 39979981, 2025). "In the control group, CD99 signaling predominantly occurred between CD4+ and CD8+ T cells and tumor cells." (PMID 40260248, 2025). "For example, the tumor‐supporting signals CD40–CD40L, BCMA–BAFF, and BAFF‐R–BAFF were described between CD4 TH and TREG cells and tumor B cells in DLBCL, CLL, and MCL." (PMID 40571973, 2025).
tumor (continued). "Similar to mice, CD39/CD73 co-expression on CD4+ and CD8+ T cells was higher in the tumor compared to PBMCs, even though to a lesser extent." (PMID 39751916, 2025). "The observed trend indicates that CAFs expressing FAP as well as CD68 + macrophages and tumor-infiltrating lymphocytes (TILs) (CD4, CD8, and CD4 + FOXP3 +) are more abundant in the more aggressive ccRCCs." (PMID 39751643, 2025). "The absolute counts of CD4 + and CD8 + T cells per gram of tumor weight showed a remarkable rise with 130H2 antibody treatment." (PMID 39743547, 2025). "The relative percentage and total numbers of CD4 and CD8 Tmt+ T cells in the spleen were analyzed after 25 days of tumor injection." (PMID 40399490, 2025). "While only about 12% and 5% of CD4+ T cells express CD39 and CD73 or CD39 alone in the spleen of naïve mice, respectively, these proportions double in spleens of tumor-bearing mice." (PMID 39751916, 2025). "Characterization of T cell subsets revealed that almost all tumor spheroid-activated T cells were CD8+, while IL-2-activated T cells were CD4+." (PMID 40123996, 2025). "Further analysis revealed an increase in tumor‐infiltrating CD8+ and CD4+ T cells in the FAST group, along with a reduction in the proportion of regulatory T (Treg) cells." (PMID 40135850, 2025). "our findings reveal a distinct immune profile with increased CD3+, CD4+, CD8+ and CD20+ lymphocytes in normal tissues adjacent to tumors and a notable presence of granzyme B+ cells in the tumor interface, particularly in patients with structural disease." (PMID 40469283, 2025). "When early disappearing tumor sites were examined, we found a large influx of SRC-3–deleted Tregs, CD8, CD4, and natural killer antitumor cells and high concentrations of interferon-gamma (Inf-γ) and granzymes and perforin—all of which are toxic to tumors." (PMID 40090583, 2025). "Within oncological contexts, CIITA augments tumor cell recognition by the immune system through upregulation of MHC II surface molecules, thereby facilitating efficient antigen presentation to CD4+ T lymphocytes 11-13." (PMID 40861816, 2025). "From the overall effect, CD4+ T cells and CD8+ T cells collaboratively exert a crucial anti-tumor effect within the TLS." (PMID 40534852, 2025). "A comprehensive reevaluation was conducted to assess the filtration levels of various immune cells, including B-cells, CD4+ T cells, CD8+ T cells, neutrophils, macrophages, and DCs (dendritic cells) in each patient’s tumor based on gene expression profiles." (PMID 40290432, 2025). "We have previously shown that CD4-, CD8-, and CD25-positive cells, in addition to tumor suppressors, play roles in the regression of established CIN2-3." (PMID 40508015, 2025). "Analysis at day 28 showed responding tumors with significant CD4+ and CD8+ infiltration (> 200 cells/mm2) either peripherally or throughout the tumor mass, correlating with MRMI enhancement patterns." (PMID 41041061, 2025). "For instance, Pexastimogene Devacirepvec (Pexa Vec), as an newly discovered OV, has shown the ability to activate natural killer (NK) cells as well as CD4+ and CD8+ T cells within tumor tissues." (PMID 41024300, 2025). "In contrast, other CD4+ T cells, aside from Tregs, as well as CD8+ T cells, demonstrate anti-tumor effects during the anti-tumor immune response." (PMID 40534852, 2025). "PDPN on lymph node stromal cells has been shown to suppress T cell proliferation and enhance tumor growth by restricting antitumor CD4+ T cell function, whereas depletion of stromal PDPN bolsters antitumor T cell activity and limits tumor progression." (PMID 41573582, 2025). "Gal1‐induced TAMs recruited CD4+CD25+Foxp3+CCR6+ Tregs through the CCL20‐CCR6 axis and culminated in impaired anti‐tumor immune responses in HCC." (PMID 39853961, 2025). "TTFields enhance the effectiveness of anti-PD immunotherapy by improving CD4+ T cells and CD8+ T infiltration via inducing ICD to increase CCL2/8 and CXCL9/CXCL10 expression of tumor cells." (PMID 40098106, 2025).